FABP4 (fatty acid binding protein 4)
Diseases named in the same sentence as FABP4 in open-access papers (continued):
Sharing a sentence is not in itself a finding about the gene and the disease.
tumor (continued). "However, unlike in our study, tumour tissues instead of stroma were used as the IHC target, and the positive rate of FABP4 was relatively low (2/50), making it a less statistically powerful prognostic biomarker." (PMID 26959740, 2016). "Moreover, FABP4 was found to be induced by VEGFA and/or the NOTCH pathway in endothelial cells, and inhibition of FABP4 blocks most of the VEGFA effects, suggesting its role in tumour angiogenesis." (PMID 26959740, 2016). "The finding that FABP4 is only expressed in tumor stromal cells and not tumor cells, could distinguish FABP4 targeting probes from the probes that are currently in use." (PMID 24732569, 2014). "Furthermore, we demonstrated that blockage of FABP4 action through either genetic ablation or neutralization approaches led to suppression of steatosis and inflammation, which may potentially attenuate HCC tumor growth." (PMID 41392988, 2025). "However, there was no statistical difference in the mRNA expression of FABP4 and MAPT between tumor tissues and normal tissues of COAD patients, but the downward trend of FABP4 and MAPT expression in tumor tissues could still be seen, which may need to be verified by more clinical samples." (PMID 36203457, 2022). "Interestingly, among patients with FABP4 expression at the tumor border, 32.6% (15 out of 46 cases) exhibited tumor lymphovascular invasion, a significantly higher rate than the 14% (7 out of 50 cases) observed in patients without FABP4 expression at the tumor border." (PMID 40106183, 2025). "Analysis of paired tumor and nontumor samples from The Cancer Genome Atlas Liver Hepatocellular Carcinoma (TCGA-LIHC) cohort showed no significant change in FABP4 expression." (PMID 41392988, 2025). "Results showed that some of the most relevant pathway’s regulators and effectors (CD36, FABP4, PLIN1, PLIN4, SCD5 and ACSL6) showed significantly lower expression in tumor tissue samples (p.adjusted < 0.01, data not shown)." (PMID 40860798, 2025). "FABP4 is overexpressed in oral squamous cell carcinoma (OSCC) of the tongue, with positive staining observed in tumour regions but not in adjacent non-tumour tissues." (PMID 41149452, 2025). "We found that the expression of FABP4 and C1QA were significantly higher in tumor tissues (T) and lymph nodes (LN) in MPR than in non-MPR patients." (PMID 39353883, 2024). "FABP4+C1q+ macrophages were more abundant in MPR patients than in non-MPR patients, especially in tumor tissues and lymph nodes." (PMID 39353883, 2024). "However, the supposed basic mechanism of an adipocyte-driven tumour progression in SARIFA-positive cancers may provide the basis for pharmacological intervention targeting the tumour cell metabolism with existing drugs such as Metformin, FABP4-inhibitors or CD36." (PMID 38123705, 2024). "ACLY, ACLS4, ACSL5, SCD1, FABP1, FABP6, and CPT1A were all found to be substantially expressed in tumor tissue, although CD36, FABP3, and FABP4 were not." (PMID 35625633, 2022). "We tested pro-tumor genes expression and PPARγ activity (FABP4 expression) in coculture, we can see both PPARγ knockout and PPARγ (D64A) THP-1 cells downregulated pro-tumor genes expression, however, PPARγ activity is not impaired in PPARγ (D64A) THP-1 cells." (PMID 28974683, 2017). "Our in vivo results identifying FABP4, IL-1β and HMOX-1 as factors influencing invasiveness and tumor growth in the bone but not in the subcutaneous site were recapitulated using bone marrow adipocyte cultures in vitro." (PMID 24240026, 2013). "Similar to FABP4, FABP5 expression did not correlate with patient age, BMI and tumor size." (PMID 40106183, 2025). "When we compared macrophages and FABP4 expression in tumor tissues in patients with or without tumor metastasis, we showed that tumors from metastatic patients had higher expression of CD163+ macrophages and FABP4 expression." (PMID 39513934, 2024).
tumor (continued). "In summary, the IHC data from tumors and lungs suggest that the expression of FABP4, FABP5, or CYP2C19 is not solely come from cancer cells but also from resident or infiltrating stromal cells in tumor and lung microenvironments, affecting TNBC tumor growth or metastasis." (PMID 31941087, 2020). "Transcriptional profiling classified the Ta tumours as luminal (high expression of luminal markers such as GATA3, PPARG, FOXA1 and XBP1 as well as differentiation markers such as UPK1A and KRT20) as well as non-aggressive (high expression of SKAP2, FABP4, MBNL2 and ID1)." (PMID 28916750, 2017).
cancer (221 papers, 2010 to 2026). A tumor composed of atypical neoplastic, often pleomorphic cells that invade other tissues. "This is distinct from cancer-associated adipocytes, which are characterized by the loss of adipocyte markers, including FABP4." (PMID 38245780, 2024). "Cancer cell dependence on readily accessible sources of fatty acids is associated with FABP4 becoming an attractive therapeutic target." (PMID 35634242, 2022). "More studies should be focused on the oncogenic role and underlying mechanisms of FABP4 in cancer development to improve the clinical outcomes of cancer patients." (PMID 35899119, 2022). "FABP4 has also been linked to the development and progression of a variety of cancers, where transcriptional regulation downstream of FABP4 is associated with cellular redox status." (PMID 35740306, 2022). "The online tool Kaplan-Meier Plotter was used to verify the association between FABP4 expression and prognosis in various cancers." (PMID 36532833, 2022). "Congruently, the overexpression of FABP4 was associated with cancer-related adipocytes, and FABP4 mediated the transport of lipids from adipocytes to OC cells." (PMID 36012230, 2022). "FABP4 is suspected to be a potential point of alternative treatments for cancers associated with the adipose microenvironment." (PMID 33809784, 2021). "The dysfunction of FABP proteins has been found to be associated with some metabolic diseases, and elevated FABP4 has been observed in many types of cancer." (PMID 29285217, 2017). "Exclusion of 1821 participants with reported unintentional weight loss over the past year, cancer, and cardiovascular disease had little effect on the results (RR per standard deviation higher FABP4 1.18 (95% CI: 0.82–1.69), P = 0.35 in model 3)." (PMID 24455402, 2013). "Owing to the close relationship between excess body weight and cancer, several studies have reported an increased association between higher FABP4 levels and obesity-related cancer, particularly endometrial, ovarian, breast, and liver cancer, suggesting its therapeutic potential in cancer treatment." (PMID 38731797, 2024). "Meanwhile, knockdown of FABP4 leads to increased levels of DNA demethylation, downregulating genetic markers associated with OvCa metastasis and reducing the survival of clonal cancer cell, which provides theoretical support for targeting FABP combined with platinum treatment." (PMID 34095111, 2021). "The association of FABP4 with LNM in cancer patients has been proposed." (PMID 34702269, 2021). "However, little is known about the causal link between circulating FABP4 level and mortality including cardiovascular death and cancer death as hard endpoints in a general population." (PMID 33597568, 2021). "This may have particular importance in the context of cancer, as FABP4 in obese individuals is associated with enhanced proliferative and migration capacity of cancer cells, contributing to metastasis and reduced survival." (PMID 30705117, 2019). "Further, we used pre‐diagnostic FABP‐4 levels to help avoid the influence of treatment on the estimates and to minimize reverse causation bias, as advanced cancer (the main cause of high mortality) can lead to weight loss, which may alter post‐diagnosis FABP‐4 levels." (PMID 40857027, 2026). "Interestingly, similar mechanisms may also play a role early in cancer development, as normal endothelial cells with FABP‐4 deficiency show significantly reduced migration and invasion." (PMID 40857027, 2026). "In cancer, FABP4 acts as a lipid mediator that promotes unsaturated FFA‐induced lipid accumulation and facilitates breast cancer metastasis." (PMID 41454478, 2026). "The increased activity of these pathways aligns with previous studies reporting enhanced cancer cell proliferation with FABP4 overexpression, underscoring the critical role of altered lipid metabolism in PDAC progression." (PMID 41481753, 2026).
cancer (continued). "Compared with partial responders, complete responders showed enrichment of FABP4 and reduced expression of cancer markers." (PMID 42316430, 2026). "In conclusion, we demonstrated the crucial role of adipocyte-derived FABP4 in the regulation of cancer stemness in HCC, and its effect was enhanced by coculture with HCC cells." (PMID 41392988, 2025). "We next sought to examine the neutralizing effect of this anti-FABP4 mAb on FABP4-driven cancer stemness." (PMID 41392988, 2025). "This strong interaction suggested anticancer potential, as FABP4 contributes to cancer (ovarian, colorectal, breast, and prostate) metastasis and progression." (PMID 40430580, 2025). "Clinical application of FABP4 also faces some challenges, such as the need to further clarify the functional heterogeneity of FABP4 across different cancers." (PMID 40717587, 2025). "The analysis results showed that Macrophages_FABP4 exhibited significant depletion in cancer tissues, while Macrophages_SLENOP, Macrophages_SPP1, Macrophages-STMN1, and Macrophages_CXCL10 showed significant enrichment." (PMID 40916017, 2025). "Specifically, FABP4, regulated by PPARγ signaling, is upregulated in cancer cells, leading to reduced intracellular lipid droplets and suppressed cell proliferation, thereby promoting lipolysis." (PMID 41369331, 2025). "To elucidate the mechanisms by which FABP4 regulates cancer stemness of HCC cells, we performed bulk RNA-seq profiling using PLC/PRF/5 cells that were pretreated with 0 ng/mL or 100 ng/mL rhFABP4 for 24 hours." (PMID 41392988, 2025). "Further exploration with Metascape highlighted associations of FABP4 and CADM1 with cancers (head and neck), while ENG was linked to congenital malformations of the circulatory system." (PMID 41398348, 2025). "Lipid transfer from adipocytes to cancer cells mediated by fatty acid binding protein 4 (FABP4) was shown to lead to increased energy generation needed by invasive cells to establish metastasis." (PMID 39964754, 2025). "Fatty acid–binding protein 4 (FABP4) was preferentially secreted by adipocytes, and recombinant FABP4 further augmented the cancer stem cell (CSC) properties of HCC cells." (PMID 41392988, 2025). "FABP4: FABP4 promotes cancer cell proliferation, motility, angiogenesis, and resistance to chemotherapy, and it also inhibits antitumour immunity." (PMID 38610991, 2024). "In the presence of external factors (e.g., tumors), FABP4 can be secreted from macrophages during lipolysis, which in turn enhances the utilization of FA ligands by cancer cells." (PMID 39513934, 2024). "There is a long list of inhibitors of FABP4, which is another protein that can serve as a target in anti-cancer therapy." (PMID 39085485, 2024). "Of the 10 members of this family, FABP4 is most frequently addressed in the context of cancer biology and therapy." (PMID 39085485, 2024). "As reported, FABP4 is required for accumulation of lipid droplets (LDs) in the intracellular compartments, and LD was reported to ease immune evasion, cancer malignant stemness, and poor prognosis of cancer patients." (PMID 39630608, 2024). "As described in the previous section, numerous studies have demonstrated that FABP4 can increase the aggressiveness of cancers, including their ability to metastasize." (PMID 39085485, 2024). "It is known that FABP4 leads to abnormal metastasis and aggression in ovarian cancer, contributing to poor prognosis for this and other types of cancers, such as glioblastoma." (PMID 36985701, 2023). "Similarly, we observed that all tested CRC cells converted adipocytes into cancer-associated adipocytes, which decreased lipid content and the expression of genes that are characteristic of adipocytes (including PPARγ, resistin, adiponectin, FABP4, perilipin, and LIPE)." (PMID 37316878, 2023). "Exogenous FABP4, delivered either directly or by coculture with adipocytes, has also been demonstrated to support cancer cell proliferation and migration." (PMID 37207357, 2023).
cancer (continued). "FABP4 has been reported to be involved in numerous types of cancer; high expression has been shown in colon cancer tissue, liver cancer stem cells, glioblastoma tissue and cell lines, ovarian cancer and acute myeloid leukemia, among others." (PMID 37207357, 2023). "FABP4 coexpressed genes were identified based on Cancer Cell Line Encyclopedia (CCLE) database, which were employed for further enrichment analysis." (PMID 36264920, 2022). "In cancer samples, we observed significant correlations between FABP4 and FABPpm (p = 0.009, r = 0.490), FATP4 and MCT1 (p = 0.009, r = 0.489), FATP4 and FABPpm (p = 0.0004, r = 0.636), and SNAT1 and GLUT1 (p = 0.005, r = 0.527)." (PMID 36012230, 2022). "Studies targeting FABP4 have shown that FABP4-inhibited cancer cells have decreased aggressiveness (less metastasis) and have an increased sensitivity to carboplatin therapy." (PMID 35634242, 2022). "Collectively, FABP4 has been found to be upregulated in most cancer types, and correlated with poor prognosis." (PMID 35899119, 2022). "First, we found that FABP4 was low-expressed in more than ten cancers through pancancer analysis of the TCGA database and then confirmed its protein expression in the CPTAC database to be lower than that in normal tissues." (PMID 36532833, 2022). "Dysregulated expression of FABP4 is associated with different clinic-parameters and prognosis, indicating FABP4 as a potential prognostic marker in different cancer types." (PMID 35899119, 2022). "Recent studies pointed out that circulating FABP4 levels have great clinical implications in cancer." (PMID 35899119, 2022). "FABP4 actively participates in dysregulated metabolism in patients with cancer through complex multisystem interactions with various signaling pathways." (PMID 36060264, 2022). "In this review, we explore the molecular mechanisms by which FABP4 promotes carcinoma development and the interaction between fat and cancer cells in obese circumstances here." (PMID 36060264, 2022). "The role of FABP4 in cancer has yet to be discovered, so in this article, we explored the potential role and mechanism of FABP4 in pancancer through bioinformatics analysis." (PMID 36532833, 2022). "We show that the ectopic addition of each of the three ligands to cancer-associated fibroblasts (CAFs) elevates the expression of CD36, as well as the adipogenic marker FABP4." (PMID 36361532, 2022). "At the same time, in the cancer cells, an increase in the fatty acid chaperone FABP4 was observed as well as an increase in β-oxidation and cancer cell growth." (PMID 35565396, 2022). "In the process of exploring the mechanism and function of FABP4 in cancer, many researchers have found that it is related to the EMT process." (PMID 36532833, 2022). "FABP4 was highly expressed on the membrane of metastasis OVC cells at the adipocyte–cancer cell interface and mediated lipid accumulation and effect on invasion." (PMID 35372362, 2022). "As a marker involved in adipocyte differentiation, FABP4 promotes the progression of feminine cancers, such as ovarian cancer, and cervical cancer." (PMID 36578551, 2022). "In models of therapy-induced hypoxia, FABP4 expression in the TME increases the formation of lipid droplets (LD) in cancer cells and contributes to cancer resistance to oxidative stress and ferroptosis." (PMID 36551752, 2022). "Targeted therapy on FABP4 was performed in cancer cells grown together with primary human omental adipocytes." (PMID 33809784, 2021). "In recent studies, FABP4 has been shown to promote cancer progression by regulating lipid metabolism, the AKT pathway and EMT." (PMID 34702269, 2021). "Circulating FABP4 concentrations are higher in females and patients with metabolic disorders, cardiovascular diseases, and cancer than in young healthy males." (PMID 33568227, 2021).